MFN2 (mitofusin 2)
Diseases named in the same sentence as MFN2 in open-access papers (continued):
Sharing a sentence is not in itself a finding about the gene and the disease.
Sepsis (18 papers, 2017 to 2025). Sepsis is defined as life-threatening organ dysfunction caused by a dysregulated host response to infection. "Taken together, these data indicate a critical role of Mfn2 in CD4+ T cell apoptosis in sepsis and the underlying mechanism of autophagy deficiency." (PMID 29358849, 2017). "Studies on sepsis-induced lung injury, caused by cecal ligation puncture or lipopolysaccharide (LPS), have shown decreased expression levels of mitochondrial fusion proteins MFN2 and OPA1 in lung tissue, alveolar epithelial cells, and macrophages." (PMID 40177356, 2025). "Given the similar trend of the in vivo and in vitro studies, we hypothesize that Mfn2 might be a regulatory factor of CD4+ T cell apoptosis in sepsis and autophagy deficiency might be the molecular mechanism." (PMID 29358849, 2017). "In contrast, NR4A1 inhibited MFN1, MFN2, and OPA1 expression, worsening lung injury caused by sepsis." (PMID 40177356, 2025). "This improvement aligns with increased expression of genes regulating mitochondrial biogenesis (SIRT-1 and PGC-1α), the promotion of the Mfn2 gene associated with mitochondrial fusion, and suppressing inflammatory response following CLP-induced sepsis." (PMID 40584438, 2025). "In sepsis, decreased Mfn2 and increased Drp1 levels lead to mitochondrial fragmentation and dysfunction." (PMID 41000071, 2025). "Some sepsis models have demonstrated a reduction in Mfn2 mRNA levels and an elevation in Drp1 mRNA levels, which are associated with mitochondrial fragmentation." (PMID 41000071, 2025). "Mitochondrial dysfunction in sepsis was manifested as elevated Drp1 expression and diminished Mfn2 expression." (PMID 35672697, 2022). "Our results showed that the expression of Drp1 and Fis1 was increased, while OPA1, Mfn1 and Mfn2 were decreased in the intestinal epithelium during sepsis, indicating increased mitochondrial fission and insufficient mitochondrial fusion." (PMID 36581806, 2022). "In our study, patients with sepsis presented with significantly decreased serum levels of parkin, Mfn2, and PGC-1α and significantly increased serum Fis1 level and Fis1/parkin, Fis1/Mfn2, Fis1/PGC-1α ratios." (PMID 34055831, 2021). "Future studies are needed to identify the upstream regulators of MFN2 that link mitochondrial dynamics, inflammatory responses, and oxidative stress during sepsis and other inflammatory diseases." (PMID 34482801, 2021). "This study found that the expression of mfn2 was significantly decreased after sepsis, resulting in insufficient mitochondrial fusion." (PMID 34039427, 2021). "In other words, elevations of parkin, Mfn2, and PGC-1α appear to protect against organ dysfunction in animal models of sepsis, whereas Fis1 is associated with sepsis severity and multiple organ dysfunction." (PMID 34055831, 2021). "Mitotherapy involving repetitive injections after CLP led to a restoration of gene expression levels of SIRT-1 (P=0.0262 vs Sepsis group), PGC-1α (P=0.0191 vs Sepsis group), and Mfn2 (P=0.0175 vs Sepsis group), bringing them closer to the levels observed in the pre-damage state." (PMID 40584438, 2025). "Consistent with references, Drp1 increased and Mfn2 decreased in the hippocampus of sepsis mice." (PMID 39258790, 2024). "In a sepsis-induced, myocardial-injured mouse model, molecules H2 promoted protein increase of HO-1, MFN2, and PGC1-1α expression, inhibited sepsis-induced mitochondrial dysfunction, and remodeled fatty acid oxidation in the heart in the sepsis model by increasing myocardial energy." (PMID 38136182, 2023). "Hence, MFN2 prevents liver inflammation, fibrosis, and sepsis and is a promising therapeutic target for liver diseases." (PMID 34482801, 2021). "Although there are a number of studies indicating that Mfn2 is associated with T cell apoptosis in sepsis, the potential role and underlying mechanism of Mfn2 in T cell apoptosis resulting from sepsis are not fully characterized." (PMID 29358849, 2017).
Sepsis (continued). "The function of Mfn2 in CD4+ T cell apoptosis in sepsis is poorly understood." (PMID 29358849, 2017). "Similarly, our results showed that the mitochondrial fusion-fission balance shifts toward mitochondrial fission during sepsis, as reflected by a decrease in MFN2 and OPA1, an increase in Drp1 translocation and Drp1 phosphorylation, and a decrease in mitochondrial size and elongated mitochondria." (PMID 31263382, 2019). "Hence, we hypothesized that Mfn2 might be involved in the regulation of CD4+ T cell apoptosis in sepsis and autophagy might be the potential mechanism." (PMID 29358849, 2017). "MMVs can deliver mfn2, PGC-1α, and functional mitochondria to intestinal epithelial cells, synergistically improve mitochondrial dynamic balance of target cells after sepsis, and restore the mitochondrial function and intestinal barrier function." (PMID 34039427, 2021). "The area under the receiver operating characteristic (ROC) curve of the Fis1/parkin ratio was greater than that of Fis1, parkin, Mfn2, and PGC-1α levels as well as that of the Fis1/Mfn2 and Fis1/PGC-1α ratios for prediction of 28-day mortality due to sepsis." (PMID 34055831, 2021). "In the current study, we stated that Mfn2 acted as a negative regulatory factor of autophagy and prompted apoptosis of CD4+ T cells in sepsis." (PMID 29358849, 2017). "To confirm the relationship between Mfn2 expression, autophagy level, and apoptosis in CD4+ T cells in sepsis, we cultured CD4+ T cells in vitro with LPS (10, 100, or 1000 ng/ml) or PBS for 24 hours." (PMID 29358849, 2017). "While levels of mitochondrial fusion-related genes Opa1 and Mfn2 were not different between groups, levels of mitochondrial fission-related genes, Fis1 and Dnm1l, were increased in Sepsis by 16% (p = 0.0197) and 42.1% (p = 0.0416), respectively." (PMID 41315622, 2025). "Therefore, to evaluate the relationship between Mfn2 expression, autophagy level, and apoptosis of CD4+ T cells in sepsis, we performed in vivo and in vitro investigations." (PMID 29358849, 2017). "However, since PINK1 and PARKIN mediate degradation of MFN2 and activation of DRP1 to prevent fusion while promoting fission, we cannot conclude that protein levels or activity of PINK1 and PARKIN and hence fusion/fission are unaltered in sepsis." (PMID 33494815, 2021). "Further, sepsis-AKI did not affect mRNA expression of the mitochondrial fusion and fission markers mitofusin 2 (MFN2) and dynamin-related protein 1 (DRP1), respectively." (PMID 33494815, 2021). "Sepsis-AKI patients had lower mRNA expression of TFAM (marker for biogenesis) and PINK and PARKIN (markers for mitophagy), but no change in mRNA expression of MFN2 and DRP1 (markers for fusion and fission)." (PMID 33494815, 2021).
liver cancer (17 papers, 2018 to 2025). An epithelial or non-epithelial malignant neoplasm that arises from the liver. "Animal models have also shown that Mfn2 reexpression reduces liver disease, while deletion of Mfn2 causes inflammation, TG accumulation, fibrosis, and liver cancer." (PMID 41010498, 2025). "Specifically, the ablation of Mfn2 in mouse livers causes inflammation, triglyceride accumulation, fibrosis, and in the last instance, liver cancer." (PMID 35625937, 2022). "The results of this study showed that MFN2 is expressed at low level in liver cancer and is associated with poor prognosis, suggesting that MFN2 is a tumor suppressor gene in HCC." (PMID 30498519, 2018). "Of note, Mfn2 re-expression is able to improve liver pathology in steatohepatitis, while the hepatic deletion of Mfn2 causes steatosis, inflammation, fibrosis, and liver cancer." (PMID 36984762, 2023). "All these conditions exposed so far are due to a reduction in Mfn2 hepatic levels, leading to a poor PS transfer and phospholipid synthesis, which causes ER stress, a NASH-like phenotype, and liver cancer." (PMID 35625937, 2022). "Other possible mechanisms by which MFN2 affects carcinogenesis have been studied in liver cancer, gastric cancer, and bladder cancer." (PMID 33479369, 2021). "MFN2 has been found to induce cell cycle arrest and mitochondrial-dependent cell death (apoptosis) in liver cancer, gastric cancer, and bladder cancer." (PMID 33479369, 2021). "Another ER-mitochondria tethering protein, MFN2, increases cell death and mitochondrial calcium influx in liver cancer cells." (PMID 32182828, 2020). "In keeping with these observations, specific deletion of MFN2 in liver causes ER stress, which leads to a chronic inflammatory state that in turn causes the activation of TGF-β1 and deposition of collagen, with the subsequent development of liver cancer." (PMID 34073868, 2021). "Intriguingly, a recent study disclosed MFN2 as a key factor in the development of non-alcoholic fatty liver disease (NAFLD) and liver cancer, due to its role in transferring PS at the EMCS." (PMID 36158205, 2022). "Consequently, hepatic Mfn2 deficiency reduces PS transfer and phospholipid biosynthesis, and promotes endoplasmic reticulum (ER) stress resulting in liver disease such as NASH and liver cancer; ablation of Mfn2 in the liver disrupts of ER-mitochondrial PS transfer." (PMID 32213662, 2020). "This investigation showed that Mfn2 liver knock-out promoted less L-serine incorporation into PS, PE, and PC, leading to endoplasmic reticulum stress and the progression of a NASH-like phenotype and liver cancer, which will be discussed further." (PMID 35625937, 2022). "In contrast to MFN1, knockout of MFN2 in liver causes a nonalcoholic steatohepatitis (NASH)-like phenotype and liver cancer, suggesting noncomplementary roles of MFN1 and MFN256." (PMID 35710796, 2022). "In addition, a negative correlation between MFN2 levels and the prognosis of liver cancer has been described." (PMID 34073868, 2021). "However, the role of MFN2 in liver cancer has not been reported yet." (PMID 30498519, 2018).
gastric cancer (15 papers, 2013 to 2025). A primary or metastatic malignant neoplasm involving the stomach. "Decreased Mfn2 also manifested the association with an aggravation in the stage of gastric cancer and a poorer overall survival." (PMID 36647167, 2023). "A recent study has shown that NPRA can enhance FAO in gastric cancer (GC) cells by protecting mitofusin 2 from protein degradation and promoting its mitochondrial localization, thereby leading to cisplatin resistance in GC cells." (PMID 40514365, 2025). "Lately, the role of YAP in activating mitophagy via the SIRT1/Mfn2 axis and its contribution in migration and viability in gastric cancer have been highlighted." (PMID 31210843, 2019). "The over-expression of MFN2 has been observed to enhance tumorigenesis while inhibition of MFN2 has been revealed to exert anti-cancer effects in human gastric cancer." (PMID 30932749, 2019). "In the current study, we examined the expression of Mfn2 in tissues from 90 gastric cancer cases and evaluated its prognostic significance in gastric cancer." (PMID 23797661, 2013). "In vitro experiments showed that Mfn2 overexpression suppressed gastric cancer cell proliferation and colony formation, weakened the invasion and migratory ability of cancer cells by downregulating MMP-2 and MMP-9, halted the cell cycle and induced apoptosis." (PMID 23797661, 2013). "In summary, we demonstrated that the expression of Mfn2 was lower in tumor tissue than in normal mucosal tissue in gastric cancer patients and that it was negatively correlated with tumor size." (PMID 23797661, 2013). "We also confirmed that Mfn2 suppressed cell proliferation, arrested the cell cycle in the G0/G1 phase, induced apoptosis and weakened the invasion ability of gastric cancer cells." (PMID 23797661, 2013). "MFN2-induced mitophagy improved disease prognosis in gastric cancer." (PMID 39246845, 2024). "In support, Sirt1 activator is shown to upregulate Mfn2 expression in gastric cancer cells." (PMID 37415667, 2023). "Moreover, Mfn2 overexpression suppresses the proliferation of gastric cancer cell through P21 and PI3K/Akt signaling." (PMID 30323195, 2018). "Therefore, Mfn2 is a potential anti-tumor gene and a potential therapeutic target for the treatment of gastric cancer." (PMID 23797661, 2013). "If we could control the expression of Mfn2, it is possible that the progression of gastric cancer could be delayed." (PMID 23797661, 2013). "Furthermore, we explored the cellular function and mechanism of Mfn2 in vitro using gastric cancer cell lines." (PMID 23797661, 2013). "Therefore, Mfn2 is a potential anti-tumor gene and a potential therapeutic target for treating gastric cancer." (PMID 23797661, 2013). "Moreover, Mfn2 could inhibit cell proliferation, induce apoptosis and weaken the invasiveness of gastric cancer by arresting cell cycle." (PMID 36647167, 2023). "In addition, studies also showed that exogenous MFN2 can inhibit the proliferation of gastric cancer cells and induce apoptosis in vitro by promoting the flow of calcium ions from the endoplasmic reticulum to mitochondria, thereby disrupting the mitochondrial calcium ion homeostasis." (PMID 30498519, 2018). "The progress of gastric cancer may be delayed by controlling Mfn2 expression." (PMID 23797661, 2013). "However, the mechanism underlying the anti-tumor effect of Mfn2 is unclear, and Mfn2 has never been studied in gastric cancer." (PMID 23797661, 2013). "Mitofusin 2 (MFN2) promotes cell proliferation and invasiveness in gastric cancer." (PMID 31796117, 2019). "Recent studies of Mfn2 in cancer research have not included gastric cancer." (PMID 23797661, 2013).
viral infection (14 papers, 2015 to 2025). "Our in vitro cleavage assay shows that 3C-protease cleaves MFN-2, displaying a similar band pattern as in the viral infection." (PMID 39677747, 2024). "To further understand how mitofusin-2 regulates EV-D68 infection, we overexpress mitofusin-2 in H1HeLa cells followed by viral infection." (PMID 39677747, 2024). "To probe the effect of SARS-CoV-2 infection onthe mitochondrial proteins, we analyzed the levels of mitochondrialouter membrane proteins Mfn1 and Mfn2 in the mouse lung tissue withoutvirus infection and on 3 or 6 days after viral infection." (PMID 38386664, 2024). "Numerous studies have shown that Mfn2 is a key regulator of innate immune responses during viral infections." (PMID 35958608, 2022). "Although MFN2 signaling has been mostly studied in the context of viral infection, recent studies suggest a role for MFN2 in regulating the interactions between bacteria and host cells." (PMID 34482801, 2021). "Numerous recent studies have shown that MFN2 is a key regulator of innate immune responses during viral infections." (PMID 34482801, 2021). "Together, these data suggest that MFN1 and MFN2 interact with MAVS to fine-tune innate immune responses during viral infection." (PMID 34482801, 2021). "It is worthy to note that virus infection alone had little effect on Mfn2 expression both in vivo and in vitro, suggesting CORT as the sole factor responsible for the alteration of Mfn2." (PMID 32943610, 2020). "This discrepancy strongly indicated that virus infection warranted CORT-induced degradation of MAVS via Mfn2 upregulation." (PMID 32943610, 2020). "They showed that the deletion-targeting of mitofusin 1 (Mfn1) and mitofusin 2 (Mfn2), two molecules involved in mitochondrial fusion, prevented cells from producing interferons and pro-inflammatory cytokines in response to viral infection." (PMID 31058096, 2019). "Virus infection triggered the association of NLRP3 with Mfn1 and Mfn2 in LPS-primed BMDM in a ΔΨm-dependent fashion." (PMID 31540165, 2019). "In accordance with this report, we also observed that overexpressed MFN2 dampened the generation of IFN-β following viral infection and increased H1N1 replication." (PMID 30792656, 2019). "Mfn2, on the other hand, is responsible for mitigating cell death induced by viral infection." (PMID 40284870, 2025). "Mfn2 is a master regulator of immune responses during viral infections." (PMID 35958608, 2022). "The accumulated data may support the key function of MFN2 in the regulation of inflammatory responses that are necessary for pathogen clearance during bacterial and viral infection." (PMID 33972668, 2021). "Furthermore, MFN2 is involved in activation of the inflammasome in macrophages during virus infection." (PMID 30876387, 2019). "However, Mfn1 and Mfn2 have different effects in different virus infections." (PMID 40284870, 2025). "However, few reports explain the roles of Mfn1 and Mfn2 in viral infection." (PMID 40284870, 2025). "MFN2 appears to be a key regulator of innate immunity, as it interacts with MAVS, NLRP3, and various other signaling molecules during viral infections." (PMID 34482801, 2021). "Specifically, MAVS and mitofusin 2 (Mfn2) have been proposed to recruit the NLRP3 protein to mitochondria in response to viral infection or non-mitochondrial NLRP3 activators." (PMID 33807807, 2021). "Different truncated Mfn2 and MAVS were overexpressed in HEK293T cells followed by virus infection." (PMID 32943610, 2020). "Conversely, Mfn2 silencing enhanced IFNβ production and IRF3 activation upon viral infection." (PMID 31540165, 2019).
viral infection (continued). "Our findings that MFN1 and MFN2 play distinct roles in DENV infection, RLR signaling for MFN1 and MMP maintaining for MFN2, support that these two similar proteins are not functionally redundant in viral infection." (PMID 26717518, 2015). "However, it is unclear whether MFN2 is involved in activating the conventional NLRP3 inflammasome complex; whether MFN2 levels affect host defense and pathogenesis during viral infection also remains unclear." (PMID 34482801, 2021).